IGF1 (insulin like growth factor 1)
Diseases named in the same sentence as IGF1 in open-access papers (continued):
Sharing a sentence is not in itself a finding about the gene and the disease.
breast cancer (continued). "No study, however, has investigated neonatal growth in relation to breast cancer risk, even though neonatal growth could be of particular importance, as it is strongly associated with neonatal IGF-1 levels." (PMID 18827810, 2008). "Association of tagging SNPs of IGF1 and breast cancer risk in the BPC3." (PMID 18596909, 2008). "As IGF1-19/-19, multiparity and early-onset breast cancer are more common in black than in white women, we aimed to study whether multiparity combined with IGF1-19/-19 increases the risk of early-onset breast cancer." (PMID 17311016, 2007). "Animal protein intake may increase breast density by increasing circulating levels of insulin-like growth factor-1, which has been linked to higher breast density and higher breast cancer risk among premenopausal women." (PMID 17949495, 2007). "Conversely, among patients with fewer than two children, the IGF1-19/-19 genotype was associated with a later age of breast cancer onset, and these women may initiate screening at a later age." (PMID 17311016, 2007). "Multiparity combined with IGF1-19/-19 was associated with an early age at breast cancer diagnosis." (PMID 17311016, 2007). "It has been suggested that contradictory findings regarding IGF1 CA-repeat lengths and breast cancer risk may be owing to differences in the methods used to determine the repeat lengths, sequencing or fragment analysis." (PMID 17311016, 2007). "The more relevant question in terms of the stem cell burden theory of breast cancer risk is whether IGF-1 and/or estrogen levels correlate with breast stem cell pool expansion." (PMID 17501995, 2007). "Higher weight and stores of body fat are linked to poorer survival and prognosis among patients with breast cancer, most likely mediated by the associated higher levels of oestrogen, insulin and bioavailable insulin-like growth factor-1 (IGF-1)." (PMID 15726121, 2005). "High IGF-1 levels are associated with increased risk for premenopausal breast cancer." (PMID 15756256, 2005). "Circulating IGF1 levels are associated with increased breast cancer risk." (PMID 16280042, 2005). "Based on our observation of a statistically significant interaction between parity and IGF1 genotype on body-weight-adjusted breast volume, it is possible that this gene could be a marker of women at higher risk for pregnancy-associated breast cancers." (PMID 15756256, 2005). "Our data suggest that BRCA1 mutation carriers who also lack the IGF1 19-repeat allele may be at a higher risk for early-onset breast cancer than BRCA1 mutation carriers with presence of the 19-repeat allele." (PMID 15756256, 2005). "Future work in this area should involve analysis of larger multiethnic samples, exploration for relevant determinants and markers of IGF1 levels in the blood, in order to resolve the issue of causal involvement of IGF1 in the aetiology of postmenopausal breast cancer." (PMID 12610514, 2003). "It has been postulated that the combined effect of oestradiol and IGF1 may stimulate proliferation in normal mammary epithelium and increase breast cancer risk." (PMID 9413957, 1997). "This suggests that elevated serum IGF-1 might increase the risk of breast cancer." (PMID 40493660, 2025). "In addition, high serum sex hormone-binding globulin (SHBG) concentrations may reduce the risk of breast cancer, while serum IGF-1 levels may be positively associated with the risk." (PMID 38000092, 2023). "Supporting evidence which links hormones and IGF to risk in breast cancer was found in a longitudinal study of 183 girls, where-in association of menarche and breast cancer risk may be due to estrone-to-androstenedione ratio and IGF-1 concentrations." (PMID 33816477, 2021). "Insulin and IGF-1 are of particular oncological interest, since both are known as growth factors for tumor cells and might provide a mechanistic link between the increased risk of obesity and breast cancer incidence and recurrence." (PMID 32819413, 2020).
breast cancer (continued). "Overall, these data suggest that the IGF1/X10 enhanced tumor formation is associated with several key candidate cancer drivers that could contribute, including Ezh2 and Hras which are known drivers in human breast cancer." (PMID 28173837, 2017). "Epidemiological studies have previously demonstrated that elevated IGF1 concentrations are associated with increased risk of premenopausal breast cancer, and current evidence also suggests similar associations between IGF1 concentrations and postmenopausal breast cancers." (PMID 27376028, 2016). "Moreover, experimental evidence suggests that a link between IGF‐1 and estrogen may explain this positive association, but perhaps only in breast cancers that express the estrogen receptor." (PMID 27734632, 2016). "In East Asians, the association between four IGF1 SNPs (rs17727841, rs2288378, rs7136446, and rs7956547) in high LD and breast cancer risk was modified by menopausal status and the minor alleles of these SNPs were associated with decreased risk of postmenopausal breast cancer." (PMID 27376028, 2016). "Hence, targeting Cyr61 and associated pathways may offer an opportunity to inhibit IGF-1 mediated Cyr61 induced breast cancer growth and invasion." (PMID 25062088, 2014). "In addition, the anti-tumor effect of SAV was examined on the growth arrest/apoptosis induction of MCF-7 cells as well as its ability to alter the insulin-like growth factor-1 (IGF-1) mediated breast cancer cell proliferation and to detect the underlying mechanisms." (PMID 22824368, 2012). "Some published results have shown an association between circulating IGF1 and breast-cancer risk, but it has been unclear whether this relationship is consistent or whether it is modified by IGF binding protein 3 (IGFBP3), menopausal status, oestrogen receptor status or other factors." (PMID 20472501, 2010). "However, they suggest that multiparous patients with the IGF1-19/-19 may not only have an earlier age at breast cancer diagnosis but also an increased risk of developing the malignancy." (PMID 17311016, 2007). "Thus, on the basis of epidemiological and experimental studies, a decrease in circulating IGF-1 levels may help reduce the risk of breast cancer, especially among members of high-risk families." (PMID 15756256, 2005). "Compelling epidemiological and clinical data show that high concentrations of IGF-1 in serum are associated with increased mammographic density (one of the strongest predictors of breast cancer risk), and also reliably predict increased breast cancer risk specifically in premenopausal women." (PMID 16457688, 2005). "Finally, ectopic growth hormone expression has been shown in a majority of specimens of normal and malignant breast tissue, and this may contribute to breast cancer risk, possibly by increasing the local level of bioavailable IGF1." (PMID 9413957, 1997). "In summary, insulinomas and IGF‐1 play a significant role in the development and progression of breast cancer, potentially affecting the efficacy of neoadjuvant therapy for breast cancer." (PMID 40550558, 2025). "Key pathways such as PI3K-Akt signaling, MAPK signaling, and breast cancer are linked with multiple targets including BRCA1, FGFR1, IGF1, AKT1, and EGF, suggesting their potential involvement in breast cancer pathology influenced by PCBs exposure." (PMID 40584614, 2025). "IGF1-Ea predominates in CRC and cervical cancer (CC), while cultured cell lines also show the presence of IGF1-Ea in EC, breast cancer (BC), and melanoma." (PMID 39796756, 2025). "To assess the influence of assay design on reproducibility, we prepared three additional sets targeting CDKN1A and IGF-1 in duplex reactions, using diluted breast cancer cDNA." (PMID 40869117, 2025). "Both insulin and IGF-1 can promote cell proliferation and inhibit apoptosis in breast cancer cells, even at physiologically relevant concentrations." (PMID 40764810, 2025).
breast cancer (continued). "PI3K signalling is a main driver of IGF-1-induced aerobic glycolysis in mouse mammary tumour cells, and mediates IGF-1-stimulated glucose uptake in mouse adipocytes." (PMID 39433211, 2025). "KL has been linked to the inhibition of insulin and insulin-like growth factor 1 (IGF-1) pathways, which regulate cell proliferation and breast cancer tumorigenesis." (PMID 40006994, 2025). "Insulin‐like growth factor‐1 (IGF‐1) and its receptor also play a crucial role in the development and progression of breast cancer." (PMID 40550558, 2025). "We found that the expression of both SPOCK1 and IGF-1 was reduced in ANXA2-knockdown breast cancer fibroblasts." (PMID 40837013, 2025). "This process additionally enhanced the activity of CCAAT/enhancer-binding protein β, a transcription factor that suppresses breast cancer growth and is negatively impacted by the IGF-1/Akt pathway." (PMID 40004457, 2025). "For example, a meta-analysis of 34 RCTs in breast cancer patients found significant reductions in insulin-like growth factor 1 (IGF-1), enhancements in muscle strength (e.g., bench and leg press performance), and decreases in BMI and body weight." (PMID 41018145, 2025). "Similar findings were later reported in MCF-7 breast cancer cells, where insulin-like growth factor 1 (IGF-1) induced oscillatory calcium elevations essential for cell-cycle progression." (PMID 41511297, 2025). "Studies have shown that IGFBP-3 and IGF-1 levels are related to the development and recurrence of breast cancer." (PMID 40493660, 2025). "Elevated circulating levels of IGF-1 and its primary binding protein, IGFBP-3, have been identified as independent risk factors for both breast cancer development and recurrence in the general population." (PMID 41157306, 2025). "Previously, in cellular models of breast cancer, it was found that IGF1 promoted CYR61-induced cell growth and invasion, suggesting a regulatory relationship between IGF1 signaling and CYR61 expression." (PMID 41009559, 2025). "Silencing ClC-3 leads to reduced proliferation, suppressed IGF-1 signalling, and decreased tumour growth in breast cancer models." (PMID 40806720, 2025). "This review focuses on observational studies examining breast cancer incidence among adults with acromegaly, a condition characterized by chronic excess of growth hormone and insulin-like growth factor-1 (IGF-1)." (PMID 41293738, 2025). "Defective GHR signaling, as seen in human Laron dwarfism, resulted in low plasma IGF-1 concentrations and limited growth, but also marked absence in the development of breast cancer and type 2 diabetes." (PMID 39459020, 2024). "Post-treatment exercise interventions have also shown beneficial impacts on IGF1 and inflammatory biomarkers in breast cancer patients." (PMID 39346906, 2024). "Whole grain foods, unlike refined foods, stabilise glycaemic and insulin levels, thus preventing the increase in the concentration of insulin-like growth factor-1 IGF-1, a risk factor for breast cancer." (PMID 38275908, 2024). "An associated study revealed that the activation of insulin-like growth factor 1 (IGF-1)/phosphoinositide 3-kinase (PI3K) signaling promotes BNIP3-mediated mitophagy in breast cancer." (PMID 39472438, 2024). "Previous studies have implicated crosstalk between ITGB1 and IGF-1R in response to IGF-1 stimulation, particularly in breast cancer and prostate cancer cells." (PMID 39608716, 2024). "The potential mechanism of action of probiotics and a ketogenic diet in inhibiting breast cancer in mice involves the modulation of the immune system and the reduction of IGF-1, but requires further investigation." (PMID 38594256, 2024). "Summary of in vitro and in vivo evidence for IGF-1 in breast cancer proliferation, migration, invasion, and metastasis." (PMID 39273251, 2024).
breast cancer (continued). "Studies have shown that lncRNA NR2F1-AS1 increased the expression of insulin-like growth factor-1 (IGF-1) through sponge absorption of miRNA-338-3p, and the activation of IGF-1 promoted the angiogenesis of HUVECs in breast cancer." (PMID 38956502, 2024). "Further research is crucial to elucidate the diverse mechanisms through which cytokines, IGF-1, mTOR, and AKT levels contribute to the increased breast cancer risk." (PMID 38254789, 2024). "In breast cancer, the IGF1/IGF1R axis triggers STAT3-dependent transcriptional activation of S100A7, a cytokine-like molecule binding to RAGE." (PMID 38892104, 2024). "Lapatinib was able to inhibit cross-signaling with IGF1 in solid cancer and breast cancer, providing a rationale for its use upon progression to trastuzumab." (PMID 38611014, 2024). "Collectively, our research highlights the important role of TAMs/CXCL1 in mediating breast cancer chemoresistance through the regulation of autophagy, and proposes IGF1/IGF1R as a potential upstream signaling that governs autophagy via STAT3/HMGB1 activation." (PMID 39394189, 2024). "Recent evidence highlights the essential roles of IGF-1 and its isoforms in breast cancer (BC) development, progression, and metastasis." (PMID 39273251, 2024). "PAPP-A and IGF1: PAPP-A's interaction with insulin-like growth factor 1 (IGF1) represents a significant axis in breast cancer development." (PMID 38623138, 2024). "This table consolidates data from studies utilizing breast cancer (BC) cell lines and xenograft animal models to explore IGF-1′s impact on key aspects of cancer behavior, including proliferation, migration, invasion, and metastasis." (PMID 39273251, 2024). "This table provides an overview of recent studies on insulin-like growth factor 1 (IGF-1) in the context of breast cancer (BC)." (PMID 39273251, 2024). "This review describes the role of obesity in endocrine-related cancers, such as prostate cancer, breast cancer and pancreatic cancer, focusing on the mechanism of IGF-1 and the crosstalk with estrogen and adipokines." (PMID 36755926, 2023). "Based on these studies, increased levels of circulating IGF-1 and IGFBP3 are considered risk factors for breast cancer." (PMID 37108716, 2023). "Extracellular AGR2 and ER-α can interact to induce the expression of IGF-1, thereby promoting the proliferation, migration and epithelial-mesenchymal transition process in breast cancer cells and enhancing drug resistance." (PMID 37197416, 2023). "In a breast cancer model, leptin and IGF-1 have been shown to increase cell proliferation and migration, and to act in synergy in terms of the activation of their receptors, indicating interactions between these two signaling pathways." (PMID 36904077, 2023). "Another report revealed that auraptene suppresses the proliferation of breast cancer cells by inhibiting the IGF-1-stimulated S phase of the cell cycle." (PMID 37958994, 2023). "Luteolin effectively blocks the rapid proliferation of luminal A subtype ERα-positive MCF-7 breast cancer cells stimulated by IGF-1 in a dose- and time-dependent manner." (PMID 37958980, 2023). "Note also that IGF-1 causes rapid methylation of ERα by PRMT1 and triggers ERα binding to the IGF-1 receptor in MCF-7 breast cancer cells." (PMID 37047814, 2023). "IGF-1 gene expression increases in people with breast cancer compared to healthy people, while the circulating levels of Insulin-like growth factor binding protein 3 (IGFBP-3) will decrease." (PMID 36849958, 2023). "IGF-1 plays an essential role in normal breast development; yet upregulation of the IGF-1 axis and increased IGF1R expression appear to be associated with the development of breast cancer." (PMID 36331687, 2023). "This was attributed to the ability of fasting/FMD to reduce the Treg population and boost CD8 infiltration by downregulating the expression of heme oxygenase-1 (HO-1) and IGF-1 and by inducing autophagy in melanoma and breast cancer." (PMID 37568713, 2023).
breast cancer (continued). "Free fatty acids (FFAs), monocyte chemoattractant protein-1 (MCP-1), CC-chemokine ligand 5(CCL5), and insulin-like growth factor 1 (IGF-1) secreted by CAAs can induce breast cancer cells to be more invasive or more proliferative." (PMID 36624542, 2023). "Emerging results have indicated that high levels of circulating IGF-1 and activated IGF-1R are associated with an increased risk of progression in several solid tumors, such as breast cancer and PCa." (PMID 36831629, 2023). "Ras proteins are accelerated by a few development factor receptors engaged in breast cancer like IGF-1, HER2, HER1, and ERα." (PMID 37228871, 2023). "The luteolin’s inhibitory effect on the IGF-1-induced breast cancer cell growth turned out to be dependent on ER α since the knockdown of ER α decreased the inhibitory effects of this substance on the IGF-1-induced cell growth." (PMID 37958980, 2023). "Data mining of clinical breast cancer specimens revealed that basal-like breast cancer patients with higher level of IGF-1 and YAP exhibit significantly shorter OS." (PMID 37081542, 2023). "•Serum testosterone and IGF-1 were more likely to impact the early state of breast cancer development." (PMID 38000092, 2023). "Exercise program alone in breast cancer patients also found improvements in IGF-1, IGFBP-1 and IGFBP-3 in maintenance of BMD." (PMID 36839371, 2023). "This review will focus on the effects of IGF-1 on the relationships between obesity and endocrine-related cancer, especially on prostate cancer, breast cancer and pancreatic cancer." (PMID 36755926, 2023). "Knockdown of AGR2 can reduce IGF-1-induced cell proliferation, migration and cell cycle progression, which indicates that AGR2 is a key regulator involved in the development of IGF-1-induced breast cancer." (PMID 37197416, 2023). "EGFR is an important factor in the RTK signaling pathway, and the IGF-1/2 neutralizing antibody m708.5 exhibits a strong synergistic effect with gefitinib, which shows benefit in the treatment of neuroblastoma and breast cancer." (PMID 36755926, 2023). "To understand the metabolic phenotype of breast cancer cells, we quantified their real-time ATP production rate upon acute stimulation with ligands—insulin-like growth factor 1 (1GF-1) and insulin." (PMID 37373357, 2023). "Eight of these (age, testosterone, age at menopause, IGF-1, alcohol intake, family history of breast cancer, age at first birth, physical activity (i.e. summed metabolic equivalent task minutes per week)) appeared in the top 20 features." (PMID 37286615, 2023). "Others have shown that CR inhibits prostate cancer and breast cancer progression partially through the regulation of the IGF1/IGF1R axis." (PMID 37686596, 2023). "This study aimed to explore the potential of CTLA-4 and IGF-1 as biomarkers for predicting the efficacy of trastuzumab treatment in HER-2-positive breast cancer." (PMID 38406785, 2023). "Overactivation of these pathways can be caused by increased circulating IGF1 levels or overexpression of IGF1R, contributing to the uncontrolled proliferation and survival of breast cancer cells." (PMID 37047814, 2023). "A previous study reports that the CBD effect on breast cancer cell proliferation can be antagonized by IGF1." (PMID 37686233, 2023). "Serum CRP, testosterone, and IGF-1 have different impacts on the transitions of different breast cancer states, confirming the role of chronic inflammation and endogenous hormones in breast cancer progression." (PMID 38000092, 2023). "According to a systematic evaluation, higher levels of IGF-1, IGFBP-3 and leptin and lower levels of adiponectin among obesity-associated protein biomarkers are correlated with an increased breast cancer risk." (PMID 36755926, 2023). "Clinically, higher level of YAP and IGF-1 significantly correlated with shorter OS in basal-like breast cancer." (PMID 37081542, 2023).